EWSR1 (EWS RNA binding protein 1)
Diseases named in the same sentence as EWSR1 in open-access papers (continued):
Sharing a sentence is not in itself a finding about the gene and the disease.
Ewing sarcoma (continued). "Ewing sarcoma derived EVs contain the EWSR1::FLI1 transcript and induce pro-inflammatory cytokine release from myeloid cells and direct them towards immunosuppressive phenotypes in vitro." (PMID 40442778, 2025). "Genetically, Ewing’s sarcoma is characterised by fusion of the EWSR1 genes, typically with the ETS gene, such as FLI1 in 90% or ERG in 5%; mergers with rarer partners are FEV, ETV1, and ETV4, but detection of these mergers alone is not diagnostic." (PMID 39941818, 2025). "Our prior results showed that treatment with the noncompetitive LSD1 inhibitor, SP-2509, reverses the transcriptional activity of both EWSR1::FLI1 and EWSR1::ERG in Ewing sarcoma." (PMID 40852926, 2025). "According to all these data, it appears that over 90% of the chromoplectic rearrangements found in Ewing sarcomas are interchromosomal translocation involving the EWSR1 and FLI1 genes." (PMID 40332527, 2025). "Imaging revealed a destructive presacral tumour with soft tissue extension, and histopathology confirmed Ewing’s sarcoma with EWSR1 rearrangement." (PMID 41250725, 2025). "The differential location and partnership identified for each of the KDM6 demethylases in Ewing sarcoma suggest that KDM6B specifies EWSR1::FLI1 for the most active regions and KDM6A signals for a specific set of enhancers that commit to neural lineage." (PMID 41085408, 2025). "This positivity led to the consideration of a differential diagnosis of Ewing sarcoma, EWSR1::NFATC2- rearranged sarcoma, and mesenchymal chondrosarcoma for further assessment." (PMID 40323235, 2025). "Ewing sarcoma tumouroids preserved characteristic EWSR1 rearrangements with erythroblast transformation-specific (ETS) family of transcription factors such as FLI1, ERG and ETV1." (PMID 41034452, 2025). "Fluorescence in situ hybridization (FISH) confirmed an EWSR1 gene rearrangement, establishing the diagnosis of Ewing’s sarcoma of the prostate." (PMID 41267731, 2025). "We identified a high frequency of fusions in Ewing’s sarcoma, where 86.2% of samples contained fusions (25 of 29 samples), including 21 samples (72.4%) harboring an EWSR1 fusion and 4 samples (13.8%) harboring a DUX4 fusion." (PMID 40711866, 2025). "In Ewing sarcoma, a delicate balance between EWSR1::FLI1 and miR-145 has been reported as an essential oncogenic component." (PMID 40442778, 2025). "It is currently in phase I/II clinical trials in EWSR1-fusion sarcomas (NCT03600649) including Ewing sarcoma, myxoid liposarcoma, and DSRCT." (PMID 40983796, 2025). "Our results showed that the abnormal signal patterns in Ewing sarcoma were deletions (2%, 8/491) and extra copies (3%, 15/491) of EWSR1 locus." (PMID 40666501, 2025). "Ewing’s sarcoma belongs to the family of small round blue cell tumors characterized by specific chromosomal translocations, most commonly involving the EWSR1 gene." (PMID 41267731, 2025). "The most important differential diagnosis for EWSR1/FUS::NFATC2 sarcoma is classical Ewing's sarcoma." (PMID 38254207, 2024). "Ewing sarcoma (EwS), a highly aggressive malignancy affecting children and young adults, is primarily driven by a distinctive oncogenic fusion, the EWSR1‐ETS, whose activity is a key source of epigenetic and clinical heterogeneity." (PMID 39524141, 2024). "Among bone and soft tissue small round cell sarcomas, the most common type is Ewing sarcoma, which is characterized by balanced translocation of the EWSR1 gene on 22q12 as a molecular genetic feature." (PMID 38254207, 2024). "The Ewing sarcoma breakpoint region 1 gene (EWSR1) on chromosome 22q12 is rearranged in Ewing sarcomas, an aggressive cancer that can sporadically occur in the kidney." (PMID 37999735, 2024). "In our review of case series of EWSR1-rearranged uterine and retroperitoneal Ewing sarcomas, VDC or VDC/IE was used in 4 of the 9 patients (44 %) whose chemotherapy regimens were reported." (PMID 39777304, 2024).
Ewing sarcoma (continued). "NKX2.2, which is a relatively specific marker for diagnosing Ewing sarcoma, can also be expressed in EWSR1/FUS::NFATC2 sarcoma." (PMID 38254207, 2024). "In this report, we present a rare extraskeletal Ewing sarcoma in a 42-year-old woman with a subcutaneous soft tissue mass in the posterior chest displaying a positive EWSR1 gene rearrangement via fluorescence in situ hybridization." (PMID 38550497, 2024). "NKX2.2 has been proven to be a very specific and sensitive marker for the diagnosis and detection of Ewing sarcoma, especially where the EWSR1::FLI1 translocation exists." (PMID 39062853, 2024). "MCC can express CD99 similar to small round cell sarcomas such as Ewing sarcoma, but will lack EWSR1 rearrangements." (PMID 39136002, 2024). "Ewing sarcoma is an EWSR1-rearranged aggressive malignancy that occurs commonly in bone and has small round blue cell morphology." (PMID 39777304, 2024). "Examination of these DRIP-seq data reveal that there is a differential enrichment in R-loops in the MSC lineage at the loci involved in the translocations described in Ewing sarcoma, such as EWSR1, FLI1, or FUS (personal observation, Figure A1 in Appendix A)." (PMID 38339014, 2024). "•Molecular evaluation, with detection of EWSR1 rearrangement in Ewing sarcoma is critical for definite diagnosis." (PMID 39777304, 2024). "The histopathological evaluation and molecular testing confirmed diagnosis of a EWSR1::FLI1 fusion Ewing sarcoma and resulted in postoperative TNM classification of ypT2b, pN0 (0/4 LN), L0, V0, Pn0, R0." (PMID 39575427, 2024). "The widespread epigenetic re-programming of Ewing sarcoma cells by EWSR1::FLI1 results in substantial heterogeneity and consistent enhancer hypomethylation." (PMID 38775200, 2024). "Along these lines, different HOX family members were found among the most upregulated genes in a BCOR::MAML3 sarcoma when compared to Ewing sarcoma with EWSR1::FLI1 fusions and CIC::DUX4 positive sarcomas." (PMID 38611033, 2024). "The Ewing sarcoma family of tumors is a group of malignant mesenchymal neoplasms characterized by characteristic EWSR1 gene rearrangements." (PMID 38254207, 2024). "Further downstream of exon 6, the EWSR1 region is flanked by 7 kb of DNA of exon-8, -9 and -10 that are regularly disrupted in Ewing sarcoma with common breakpoints in intron-7 and -8." (PMID 39769457, 2024). "In Ewing sarcoma, BACH1 downregulates EWSR1, an RNA-binding protein that mediates the transcription percent of cell cycle protein D1a and D1b by raising the transcription elongation rate of Ewing sarcoma cells." (PMID 38321558, 2024). "Sarcomas are often defined by characteristic gene fusions which are the results of chromosomal structure rearrangement, for instance the EWSR1-ETS fusions in Ewing sarcoma." (PMID 38434982, 2024). "In this Ewing sarcoma cell model, EWSR1::FLI1 is efficiently downregulated upon doxycycline-mediated expression of a specific shRNA designed against the EWSR1::FLI1 chimeric mRNA." (PMID 37511533, 2023). "We propose that EA1 has a novel propensity to bind TGA repeats at enhancers, similar to EWSR1::FLI1 binding of GGAA microsatellites in Ewing sarcoma." (PMID 38136296, 2023). "MYBL2 has been identified as a direct target of EWSR1::FLI1 with germline polymorphisms associated with activation in Ewing sarcoma and RRM2 overexpression is associated with poor prognosis Ewing sarcoma." (PMID 36793594, 2023). "We detected EWSR1 fusions in three patients with Ewing sarcoma as well as a FOXO1 fusion in a patient with rhabdomyosarcoma, confirming the specificity of our assay." (PMID 36805676, 2023). "Taken together, these data suggest that loss of hnRNPH1 partially phenocopies the effects of MS0621 on EWSR1::FLI1-dependent phenotypes in Ewing sarcoma." (PMID 36793594, 2023).
Ewing sarcoma (continued). "Although clinical applications of the CRISPR-Cas9 strategy in targeting the EWSR1::FLI1 fusion in Ewing’s sarcoma remain to be seen, there has been recent development of small molecule inhibitors to target the genetic fusion proteins of EWSR1::FLI1." (PMID 36980578, 2023). "To better understand the clinical applicability of cfDNA assays, we developed a hybridization capture-based panel targeting the most common translocation partners in two pediatric cancers, specifically EWSR1 for Ewing sarcoma and FOXO1 in ARMS5." (PMID 36805676, 2023). "EWSR1 and EWSR1::FLI1 are known to cooperate to recruit the SWI/SNF complex to EWSR1::FLI1-bound loci, and SWI/SNF components have been implicated in Ewing sarcoma." (PMID 36793594, 2023). "The Ewing sarcoma region 1 gene (EWSR1) was originally identified in the pediatric bone cancer, Ewing sarcoma, as a part of an aberrant fusion gene with FLI1." (PMID 36875767, 2023). "The study demonstrated that the knockdown of EWSR1 in the Ewing sarcoma cells facilitates the interaction between the EWSR1 proteins and the 3’ untranslated region of PRAS40 (Akt substrate) mRNA, ultimately leading to the increased levels of PRAS40 protein." (PMID 36875767, 2023). "Molecules were scored based on their ability to affect FAIRE signal at two FAIRE-enriched, EWSR1::FLI1-bound sites in Ewing sarcoma relative to regions of FAIRE signal shared by multiple cell types." (PMID 36793594, 2023). "The stability of EWSR1::FLI1 mRNA in approximately 10% of Ewing sarcomas is regulated by the carcinoembryonic RNA-binding protein LIN28B." (PMID 36672331, 2023). "Ewing sarcoma (EWS) is a small round cell sarcoma characterized by a fusion of a FET gene family member (most commonly EWSR1) and an ETS gene family member." (PMID 36983010, 2023). "The study demonstrated that the haploinsufficiency of the EWSR1 drives the Ewing sarcoma development." (PMID 36875767, 2023). "In this review, we summarize the contemporary molecular understanding of Ewing sarcoma, and the post-transcriptional and post-translational regulatory mechanisms that control EWSR1::FLI1 function." (PMID 36672331, 2023). "In our study, in order to identify the isoforms preferentially upregulated upon EWSR1::FLI1 knockdown in Ewing sarcoma A673 cells (that is, in the EWSR1::FLI1low phenotype), we analyzed in detail our RNAseq dataset." (PMID 37511533, 2023). "The RNA-binding protein HNRNPH1 was shown to facilitate Ewing sarcoma cells to properly express EWSR1 exon 8 genomic breakpoint fusions." (PMID 36672331, 2023). "We were able to identify EWSR1 fusions in 10 of the 12 patients with Ewing sarcoma, including two patients who had a CNA-negative LP-WGS profile at diagnosis, one with localized (patient 28) and one with metastatic disease (patient 26)." (PMID 36805676, 2023). "A biopsy of the femoral lesion was consistent with Ewing sarcoma, with confirmation by reverse-transcription polymerase chain reaction (RT-PCR) of tumor RNA demonstrating EWSR1::FLI1 gene fusion." (PMID 36980535, 2023). "Recently, it has been proposed that EWSR1::FLI1 levels can fluctuate in Ewing sarcoma cells, giving rise to two cell populations." (PMID 37511533, 2023). "Nonetheless, in approximately 15–20% of Ewing sarcomas, EWSR1 is fused with members of the ETS family other than FLI1, most frequently ERG." (PMID 37815662, 2023). "Histone deacetylase inhibitors have also been shown to affect Ewing sarcoma cell proliferation possibly through EWSR1::FLI1-mediated transcription and chromatin regulation, although they have yet to demonstrate a clear signal in clinical testing." (PMID 36672331, 2023). "Our research group has predominantly focused on looking up genes regulated positively or negatively by EWSR1::FLI1 in Ewing sarcoma cells (e.g., NR0B1/DAX1, CCK, LOX, SPRY1, DKK2, or FEZF1)." (PMID 37511533, 2023).
Ewing sarcoma (continued). "Next, we analyzed if the low expression of CD44 in A673 cells (EWSR1::FLI1high) was also observed in other Ewing sarcoma cells and/or other sarcoma types." (PMID 37511533, 2023). "EWSR1 (Ewing sarcoma breakpoint region 1) was originally identified as a part of an aberrant EWSR1/FLI1 fusion gene in Ewing sarcoma, the second most common pediatric bone cancer." (PMID 36875767, 2023). "Our data indicate that CD44 expression was upregulated upon EWSR1::FLI1 knockdown, and thus it is expressed in the EWSR1::FLI1low phenotype of Ewing sarcoma cells." (PMID 37511533, 2023). "In Ewing sarcoma, EWSR1 interacted with REST, and EWSR1 reduced genes are a subset of neuronal genes that contain RE1." (PMID 37892159, 2023). "Ewing’s sarcoma (ES) is a prototype characterised by EWSR1:FLI1 fusion or EWSR1 fusion with other partners." (PMID 37681936, 2023). "O-GlcNAcylation of EWSR1::FLI1 was also reported to positively regulate oncogenic function in Ewing sarcoma." (PMID 36672331, 2023). "In Ewing sarcoma, the EWSR1::FLI1 fusion oncoprotein binds GGAA repeats in microsatellite regions to generate novel enhancers." (PMID 38136296, 2023). "EWSR1::FLI1, found in Ewing sarcoma (EWS), gains the interaction with the SWI/SNF complex and guides it to genes having GGAA microsatellite repeats, enabling oncogenic gene transcription." (PMID 37093326, 2023). "EWSR1::FLI1 is necessary to maintain Ewing sarcoma proliferation and survival and exerts an ability to transform human primary mesenchymal stem cells." (PMID 36672331, 2023). "EWSR1 was discovered in Ewing’s sarcoma and neuroectodermal malignancies as a translocation-generated fusion gene between EWSR1 and FLI1 (Friend leukemia integration 1 transcription factor)." (PMID 36615603, 2023). "EWSR1 is involved in many other translocations across sarcoma subtypes, including EWSR1::FLI1 in Ewing sarcoma." (PMID 38136296, 2023). "For instance, the Ewing sarcomas are characterized by a fusion of the EWSR1 gene and FLI1 gene (85% of cases)." (PMID 37497116, 2023). "A study on a large cohort of Moroccan patients with Ewing's sarcoma showed that the combination of EWSR1 rearrangement and CD99 immunostaining is more sensitive and specific than each test alone." (PMID 36164527, 2022). "Ewing sarcoma family of tumors is a high-grade malignant tumor characterized by EWSR1 gene rearrangement." (PMID 36415387, 2022). "Tumors harboring EWSR1 gene rearrangements include Ewing sarcoma, myxoid liposarcoma, clear cell sarcomas and myoepithelial neoplasms." (PMID 33715971, 2022). "In case #2 with relapsed EWSR1:FLI1-positive Ewing sarcoma, serial viable tissue sampling with DSP before and after therapy allowed us to monitor the evolution of drug resistance under multiagent chemo- and targeted therapy." (PMID 36575299, 2022). "Since a differential diagnosis of Ewing's sarcoma is difficult, the EWSR1 rearrangement combined with CD99 immunostaining allowed us to give an exact classification for each patient and differentiated between the different entities." (PMID 36164527, 2022). "Regulation of the level of EWS::FLI1 fusion protein in Ewing sarcoma cell begins with activation of the EWSR1 promoter, which serves as the promoter of the fusion gene." (PMID 36505823, 2022). "In Ewing sarcoma, disruption of AP1B1, a neighboring gene of EWSR1, has been shown to be caused by bridged chromoplectic rearrangements also fusing EWSR1 and FLI1." (PMID 36232302, 2022). "In the biopsy specimen, a break-apart fluorescence in situ hybridisation (FISH) for EWSR1 and SS18 rearrangement was done which detected EWSR1 rearrangement and hence the diagnosis was changed from synovial sarcoma to Ewing’s sarcoma/PNET." (PMID 36405939, 2022). "These EWSR1–FLI1low cells would therefore be resistant to chemotherapy and potentially responsible for the late relapses that so frequently occur in Ewing sarcoma, usually with fatal results." (PMID 34359682, 2021).
Ewing sarcoma (continued). "Sarcomas harboring EWSR1-NFATc2 fusions have historically been categorized and treated as Ewing sarcoma." (PMID 34021224, 2021). "Further, AR signaling promoted increased R-loop formation in the EWSR1 gene and drove chromosomal breakage at high frequency at the same genomic locus that is rearranged in Ewing sarcoma." (PMID 34409300, 2021). "EWSR1-NFATc2 fusion positive sarcomas were genomically distinct from traditional Ewing sarcoma and demonstrated upregulation of the mTOR pathway." (PMID 34021224, 2021). "GGAA repeats are critical regulatory elements in Ewing’s Sarcoma, a disease driven by a translocation of the EWSR1 gene to the DNA binding domain of ERG or FLI1, ERG’s closest homolog in the ETS family." (PMID 34314419, 2021). "We then used prostate cancer cells as a model to show androgen driven formation of a break in EWSR1 at the same breakpoint hotspot that creates the EWSR1/FLI1 oncogene in Ewing sarcoma." (PMID 34409300, 2021). "EWSR1-NFATc2 fusion positive sarcomas demonstrate a unique secondary genomic profile from other Ewing sarcomas driven by mTOR signaling." (PMID 34021224, 2021). "The ntEWS PAS is in close genomic proximity to the sequence in EWSR1 that recurrently rearranges with FLI1 in Ewing sarcoma, the breakpoint hotspot." (PMID 34409300, 2021). "While EWSR1 has long been known to be involved in gene fusions in Ewing sarcoma and several other tumor entities, the role of PLAGL1 in tumorigenesis is not yet fully understood." (PMID 34355256, 2021). "We identified a number of promising therapeutic targets for this rare disease, including EWSR1, the proposed driver of Ewing Sarcoma development." (PMID 34662337, 2021). "The Ewing sarcoma breakpoint region 1 (EWSR1) gene is well known to fuse with various partner genes and involved in promoting the development of multiple sarcomas, especially the Ewing sarcoma family of tumors." (PMID 34612781, 2021). "On the other hand, EWS-FLI1 has a dominant negative effect on some EWSR1 activities in Ewing sarcoma." (PMID 34035145, 2021). "Takahashi and his colleagues reported that EWSR1–ETS fusion activated hTERT expression in Ewing’s sarcoma by recruiting p300 to TERT promoter in an ETS factor binding site-independent manner." (PMID 34221969, 2021). "Ewing sarcoma is genetically characterized by binding of EWSR1 or other members of the TET/FET family to members of the ETS family." (PMID 34203801, 2021). "Chimeric proteins resulting from chromosomal translocations between EWSR1 and various TF genes are involved in tumorigenesis such as Ewing sarcoma in bones and bone connective tissues." (PMID 33608545, 2021). "Ewing sarcoma are genetically stable tumors characterized by a chromosomal translocation leading to fusion of the EWSR1 gene on chromosome 22 and variable members of the ETS family of transcription factors." (PMID 31811703, 2020). "There was general agreement that EWSR1-ETS gene family fusions should be included on the primary arm of a future Ewing sarcoma clinical trial." (PMID 33488267, 2020). "The 2020 WHO classification of soft tissue and bone tumours defines Ewing sarcoma as a small round cell sarcoma showing gene fusions involving one member of the FET family of genes (usually EWSR1) and a member of the ETS family of transcription factors." (PMID 33050651, 2020). "This oncogenic factor is generated by a chromosomal translocation, in which a large portion of the prion-like domain (PLD) of EWSR1 is fused to the transcription factor FLI1 in Ewing’s sarcoma." (PMID 33138914, 2020). "Extra-axial tumors and cases with a diagnosis of Ewing sarcoma (EWSR1-ETS family fusions) were excluded." (PMID 32997853, 2020). "DNA methylation profiling of an EWSR1-NFATC2 fusion-positive tumour revealed a pattern that segregated out in a homogenous cluster distinct from Ewing sarcoma samples with EWS-ETS translocations, providing evidence that this subclass has unique biology." (PMID 33488267, 2020).